NCK1 (NCK adaptor protein 1)
Description:
Adapter protein which associates with tyrosine-phosphorylated growth factor receptors, such as KDR and PDGFRB, or their cellular substrates. Maintains low levels of EIF2S1 phosphorylation by promoting its dephosphorylation by PP1. Plays a role in the DNA damage response, not in the detection of the damage by ATM/ATR, but for efficient activation of downstream effectors, such as that of CHEK2. Plays a role in ELK1-dependent transcriptional activation in response to activated Ras signaling. Modulates the activation of EIF2AK2/PKR by dsRNA. May play a role in cell adhesion and migration through interaction with ephrin receptors.
Synonyms: Nck-1; NCK; NCKalpha
Tractability: Antibody: its Gene Ontology location is reachable by antibodies, with high confidence. PROTAC: ubiquitination databases record sites on it; its protein half-life has been measured.
Target class: Other cytosolic protein
Gene: Protein-coding gene on chromosome 3 (136,862,177 to 136,951,606, forward strand). Ensembl gene ENSG00000158092.
Subcellular location: Cytoplasm; Endoplasmic reticulum; Nucleus
Subcellular location (Human Protein Atlas): Cytosol; Plasma membrane
Pathways (Reactome):
Signal Transduction: Downstream signal transduction; RHO GTPases Activate WASPs and WAVEs; RHOU GTPase cycle; RHOV GTPase cycle; VEGFA-VEGFR2 Pathway
Immune System: Antigen activates B Cell Receptor (BCR) leading to generation of second messengers; Generation of second messenger molecules; PKR-mediated signaling; Regulation of actin dynamics for phagocytic cup formation
Developmental Biology: Activation of RAC1; DCC mediated attractive signaling
Disease: FCGR3A-mediated phagocytosis; Potential therapeutics for SARS
Cell-Cell communication: Nephrin family interactions
Gene Ontology:
Molecular function: cadherin binding; eukaryotic initiation factor eIF2 binding; molecular condensate scaffold activity; protein binding; protein kinase inhibitor activity; protein sequestering activity; protein-macromolecule adaptor activity; receptor tyrosine kinase binding; signaling adaptor activity; signaling receptor binding; cytoskeletal anchor activity; ephrin receptor binding; signaling receptor complex adaptor activity; protein domain specific binding
Biological process: antiviral innate immune response; negative regulation of insulin receptor signaling pathway; negative regulation of PERK-mediated unfolded protein response; negative regulation of T cell receptor signaling pathway; negative regulation of transcription by RNA polymerase II; positive regulation of actin filament polymerization; positive regulation of cap-dependent translational initiation; positive regulation of cap-independent translational initiation; positive regulation of endoplasmic reticulum stress-induced intrinsic apoptotic signaling pathway; positive regulation of T cell proliferation; positive regulation of transcription by RNA polymerase II; positive regulation of translation in response to endoplasmic reticulum stress; regulation of translation initiation in response to endoplasmic reticulum stress; response to endoplasmic reticulum stress; T cell activation; cell migration; ephrin receptor signaling pathway; signal complex assembly; regulation of transcription by RNA polymerase II
Cellular component: cytoplasm; cytosol; endoplasmic reticulum; protein phosphatase type 1 complex; ribosome; plasma membrane; cell-cell junction; nucleus; vesicle membrane
Genetic constraint (gnomAD): Loss-of-function variants: 19 observed, 38.7 expected, observed/expected ratio (o/e) 0.49, 90% interval 0.34 to 0.72. The upper end of that interval is the gene's LOEUF score, 0.72, which puts it in group 2 of 6, group 1 being the genes least tolerant of losing a copy. Missense variants: 358 observed, 468.98 expected, observed/expected ratio (o/e) 0.76, 90% interval 0.7 to 0.83. Synonymous variants: 165 observed, 164.49 expected, observed/expected ratio (o/e) 1, 90% interval 0.88 to 1.14.
Homologues: Orthologues: chimpanzee NCK1 (100% identical), macaque NCK1 (100% identical), rabbit NCK1 (99% identical), dog NCK1 (99% identical), rat Nck1 (99% identical), mouse Nck1 (99% identical), guinea pig NCK1 (98% identical), pig NCK1 (98% identical), tropical clawed frog nck1 (87% identical), zebrafish nck1b (78% identical), zebrafish nck1a (57% identical), Drosophila melanogaster dock (46% identical), and 1 more. Paralogues in human: NCK2 (69% identical), GRAP (17% identical), GRB2 (17% identical), GRAP2 (16% identical), SLA (12% identical), GRAPL (12% identical), DAPP1 (12% identical), SH2D5 (11% identical), SLA2 (11% identical).
Diseases named in the same sentence as NCK1 in open-access papers:
NCK1 is named in the same sentence as 39 diseases in open-access papers, as found by Europe PMC text mining. Sharing a sentence is not in itself a finding about the gene and the disease. The quoted sentences say what the papers report.
breast carcinoma (9 papers, 2009 to 2024). "A previous study suggested that NCK1 activity is important for invadopodia formation and degradation of the external matrix in metastatic breast cancer cells and melanoma cells." (PMID 39066315, 2024). "NCK1 is an tyrosine kinase that regulation cell adhesion and has role in breast carcinoma cell invasion and metastasis." (PMID 32139710, 2020). "Silencing Nck1/2 with siRNA and shRNA decreases the 3D migration of the breast cancer cell line MDA-MB-231 by dysregulating actin dynamics and invadosome formation." (PMID 30818851, 2019). "Notably, during the course of this investigation, NCK1 and NCK2 were identified as drivers of breast cancer progression and metastasis." (PMID 37479911, 2023). "Further investigation is needed to understand the mechanisms by which NCK1 and NCK2 signalling in development may be abnormally activated in breast cancer." (PMID 37479911, 2023). "In breast cancer cell lines (MDA-MB-231 cell line), this synergistic effect is mediated by the phosphorylation of eif2α (serine 51) through a decreased of the expression of Nck1 (NCK Adaptor Protein 1), a potent inhibitor of eif2α phosphorylation." (PMID 34356673, 2021). "We show that a decrease in adaptor protein Nck1, but not Nck2, is necessary for cell killing in both ER positive and ER negative breast cancer cell lines." (PMID 23706161, 2013). "Considering actin as loading control, Nck1 protein levels were significantly increased in T-47D cells, decreased in MDA-MB-231 cells and not change in MCF7 cells compared to MCF-10A cells, excluding a potential correlation between Nck1 expression levels and breast cancer progression." (PMID 21992144, 2011). "Independently of estrogen receptor expression (ER+: MCF-7 and T-47D; ER-: MDA-MB-231) or epithelial/mesenchymal phenotype (epithelial-like low invasion: MCF-7 and T-47D; mesenchymal-like high invasion: MDA-MB-231), Nck1 protein levels in breast cancer cells were not consistent with the cancer stage." (PMID 21992144, 2011).
atherosclerosis (5 papers, 2021 to 2024). A disease characterized by the build-up of fatty material and calcium deposition in the arterial wall resulting in partial or complete occlusion of the arterial lumen. "NCK1 is reported to be involved in different pathways leading to the progression of atherosclerosis." (PMID 38811951, 2024). "Atherosclerosis-prone global Nck1 knockout mice show reduced smooth muscle cell incorporation into the plaque, which is typically driven by smooth muscle phenotypic modulation, migration, and proliferation." (PMID 34124074, 2021). "Given the non‐redundant roles of NCK1 and NCK2 in inflammation and atherosclerosis, we hypothesized that NCK1 might play an important role in platelet activation and thrombosis." (PMID 38922767, 2024). "Several proteins downregulated in eWAT, such as PADI2, PSAP, NCK1, and NPM1, with proven pro-inflammatory properties that are normally secreted into the extracellular space, have been linked to the progression of atherosclerosis." (PMID 38017481, 2023). "Moreover, atherosclerosis-prone ApoE knockout mice with a global Nck1 deletion show significantly reduced atherosclerotic plaque formation associated with diminished proinflammatory gene expression and leukocyte-positive plaque area." (PMID 34124074, 2021). "Male and female Nck1-null atheroprone mice enabling inducible, endothelial-specific Nck2 inactivation were fed a high fat diet (HFD) for 8 or 16 weeks to model atherosclerosis initiation and progression, respectively." (PMID 36035930, 2022). "During atherosclerosis progression, however, abrogation of endothelial NCK2 signaling ameliorates inflammation of the arterial wall in both sexes, whereas severity of lesions and atherosclerosis progression are reduced in male, but not female, Nck1-null atheroprone mice." (PMID 36035930, 2022).
diabetes (4 papers, 2013 to 2024). "NCK1 deficiency increases pancreatic cell survival in response to diabetes-related stresses." (PMID 36360783, 2022). "Our finding suggests a possible role for glomerular NCK1 in the pathogenesis of nephropathy in patients with diabetes." (PMID 23441190, 2013). "Furthermore, some of these genes, such as NCK1, play an important role in diabetes by modifying PERK activation and signalling." (PMID 36360783, 2022). "Following further adjustment of the model for BMI, smoking status, lipid measurements, hypertension, and diabetes status, the quantitative difference of galectin-4 for CHD and NCK1 for CIMT remained significant." (PMID 38811951, 2024).
virus infection (4 papers, 2017 to 2024). "RNAi of another WASP regulator wip-1 also reduced viral load, suggesting that WIP-1 shares a similar function with NCK-1 in promoting viral infection." (PMID 37131627, 2023). "To determine whether TNK2, WASL, and NCK1 act in a common or distinct pathway for virus infection, we performed genetic epistasis analysis by generating double and triple mutant cell lines." (PMID 31769754, 2019). "TNK2, WASL, and NCK1 are in a pathway supporting virus infection." (PMID 31769754, 2019). "In this study, we further asked whether their respective human orthologues TNK2, WASL, and NCK1 play any roles in mammalian virus infection." (PMID 31769754, 2019). "There are only limited studies linking WASL and NCK1 to virus infection." (PMID 31769754, 2019). "We further demonstrated that TNK2, WASL, and NCK1 function in a pathway to support EMCV virus infection with WASL and NCK1 lying downstream of TNK2." (PMID 31769754, 2019). "The magnitude of the impact of TNK2 KO1 was greater than that of WASL KO or NCK1 KO, suggesting that TNK2 might work through additional pathways in mediating virus infection besides acting through WASL and NCK1." (PMID 31769754, 2019). "To determine whether wsp-1, the C. elegans orthologs of genes that interact with TNK2 (lst-1, dhs-7, and nck-1), or C. elegans genes that interact with WSP-1 (mig-13, mig-2, and nck-1) affect Orsay virus infection, we performed RNAi knockdown and evaluated Orsay virus replication." (PMID 28874467, 2017).
colorectal cancer (3 papers, 2019 to 2025). A primary or metastatic malignant neoplasm that affects the colon or rectum. "And the metastasis-promoting role of NCK1 has been reported in multiple cancer types, such as colorectal cancer and BC." (PMID 31214250, 2019). "NCK1 promotes angiogenesis in cervical squamous cell carcinoma and ovarian cancer via the RAC1/PAK1/MMP2 axis and in colorectal cancer via the NCK1/STAT3/PAK1/ERK axis." (PMID 40001545, 2025). "NCK1 is adaptor protein that is downstream of receptor tyrosine kinase and STAT3 signaling; both NCK1 and the other correlated gene, SLC35G2, may be involved in colorectal cancer pathogenesis." (PMID 30767760, 2019).
melanoma (3 papers, 2011 to 2026). A malignant, usually aggressive tumor composed of atypical, neoplastic melanocytes. "Our multi-omics analysis revealed PRKD1, JUN, and NCK1 as key resistance nodes, offering potential targets for therapeutic strategies to counter resistance in melanoma." (PMID 41708984, 2026). "Originally the Nck1 cDNA was isolated from a human melanoma cDNA expression library using a monoclonal antibody produced against the human melanoma-associated antigen, which has no similarity with Nck1." (PMID 21992144, 2011). "Interestingly, Nck1 protein levels normalized according to actin or tubulin loading control were comparable among the human melanoma cell lines investigated." (PMID 21992144, 2011). "However, our results demonstrate that increased endogenous expression of Nck2 in human metastatic melanoma cells relative to primary melanoma cells and melanocytes results from increased Nck2 transcription, suggesting that Nck1 and Nck2 promoters are under different regulatory controls." (PMID 21992144, 2011). "This suggests that the Nck1 mRNA might be abundant in human melanoma." (PMID 21992144, 2011). "In the linear range of PCR amplification, no significant change in Nck1 mRNA levels was detected in all human melanoma cell lines and compared with HEM." (PMID 21992144, 2011). "Nck2 siRNA transfection of 451Lu metastatic melanoma cells resulted in decreased Nck2 protein and mRNA levels, while Nck1 protein and mRNA levels were not altered." (PMID 21992144, 2011). "In this study, the effect of Nck1 overexpression on melanoma phenotype was not addressed." (PMID 21992144, 2011).
dyslipidemia (2 papers, 2021). "The Nck1 gene localizes to chromosome 3q21 in a region mutated in various cancers, and genome-wide association studies (GWAS) link Nck1 single nucleotide polymorphisms (SNPs) with obesity, dyslipidemia, circulating leukocyte counts, platelet counts, and coronary artery disease." (PMID 34124074, 2021). "Additionally, the expression of EPGN, LGR5, NCK1, PGRMC2, and VIP were also comfired at transcriptional using qPCR, indicating that those genes are closely linked to dyslipidemia in OSA." (PMID 34880901, 2021).
non-small cell lung carcinoma (2 papers, 2023). A group of at least three distinct histological types of lung cancer, including non-small cell squamous cell carcinoma, adenocarcinoma, and large cell carcinoma. "Mir-374-5p has been reported to inhibit non-small cell lung cancer proliferation and migration via targeting of NCK1." (PMID 37958433, 2023). "miR-374a-5p can suppress the proliferation and migration of non-small cell lung cancer cells via targeting NCK1." (PMID 36768914, 2023).
anxiety disorder (1 paper, 2022). A category of psychiatric disorders which are characterized by anxious feelings or fear often accompanied by physical symptoms associated with anxiety. "Moreover, our research shows that Nck1 may serve as a target for pharmacological treatment of fear and anxiety disorders." (PMID 36371406, 2022).
Arterial thrombosis (1 paper, 2024). The formation of a blood clot inside an artery. "Nck adaptor proteins (NCK1) deficiency significantly suppress the activity of platelets and arterial thrombosis." (PMID 38922767, 2024).
breast tumor (1 paper, 2025). "In rat breast tumor cells, Nck1 activity underscores its essential role in cell membrane protrusion and invasive behavior." (PMID 40575485, 2025).
Cocaine addiction (1 paper, 2025). "By broadening our perspective to incorporate the KEGG pathways, we also observed that ERBB2 (Hypo), NCK1 (Hypo), and JUN (Hyper) are members of the ErbB signaling pathway, while BDNF (Hyper) and JUN (Hyper) are constituents of the Cocaine addiction pathway." (PMID 40217422, 2025).
cutaneous melanoma (1 paper, 2019). A primary melanoma arising from atypical melanocytes in the skin. "NCK1 mutations were enriched in some cancer types, including uterine endometrioid carcinoma (P = 1e−16), stomach adenocarcinoma (P = 6.679e−06), cutaneous melanoma (P = 2.63e−05), but not BC (P > 0.05) (Binominal test)." (PMID 31214250, 2019).
Granuloma (1 paper, 2019). A compact, organized collection of mature mononuclear phagocytes, which may be but is not necessarily accompanied by accessory features such as necrosis. "Among the enrichment score-driving critical genes of the TCR signaling, the levels of transcripts for ITK and its signaling components such as LCK, GRB2, SLP76, NCK1, FYN, and PLCG are significantly upregulated in caseated granulomas compared to uninvolved lung tissue." (PMID 32038633, 2019).
Hyperglycemia (1 paper, 2013). An increased concentration of glucose in the blood. "Together, these results provide evidence of a connection between glomerular NCK1 and DN and implicate an important role for glomerular NCK1 in DN pathogenesis under hyperglycemia." (PMID 23441190, 2013). "However, little is known about relationship between hyperglycemia and NCK1." (PMID 23441190, 2013).
Insulin resistance (1 paper, 2014). Increased resistance towards insulin, that is, diminished effectiveness of insulin in reducing blood glucose levels. "Since Akt is a critical node in regulating insulin and growth factor biological actions, our findings contribute to identify Nck1 as a potential target in therapeutic strategies for insulin resistance and cancer." (PMID 25398386, 2014). "Whole-body Nck1 knockout mice are resistant to HFD-induced insulin resistance and ER stress, resembling the phenotype of liver-specific PTP1B knockout mice." (PMID 25398386, 2014). "Given that Nck1 interacts with PTP1B and modulates PTP1B protein expression as we demonstrate here, it is plausible that the protective effect of Nck1 deficiency against HFD-induced insulin resistance and ER stress could be attributed to PTP1B downregulation in liver of Nck1−/− mice." (PMID 25398386, 2014).
insulinoma (1 paper, 2022). "Interestingly, the SH2 domain of Nck1 and Nck2 has been found to mediate the interaction with phospho-PERK at Tyr-561 (Y561) in mouse insulinoma MIN6 cells and limit PERK activation." (PMID 35902806, 2022).
ischemia (1 paper, 2007). A hypoperfusion of the BLOOD through an organ or tissue caused by a PATHOLOGIC CONSTRICTION or obstruction of its BLOOD VESSELS, or an absence of BLOOD CIRCULATION. "Interestingly, Nck-1 showed a decreased association with the insoluble components during the course of ischemia, whereas this pattern was reversed upon reperfusion." (PMID 17199894, 2007). "A PY containing Nck-1 protein was detected as increasing during the first hour of ischemia, and decreasing during the first hour of reperfusion." (PMID 17199894, 2007). "Mass spectrometry identification of Nck-1 binding partners has allowed us to formulate the hypothesis that Nck-1 could be related to the ischemia-induced actin reorganization." (PMID 17199894, 2007).
meningioma (1 paper, 2020). A generally slow growing tumor attached to the dura mater. "NBAS, TIMP2, and NCK1 were few of the key proteins found to be altered in Atypical meningiomas." (PMID 32974197, 2020).
metastatic melanoma (1 paper, 2011). A melanoma that has spread from its primary site to another anatomic site. "Particularly, we observed significant higher levels of Nck2 protein and mRNA, as opposed to no change in Nck1, in human metastatic melanoma cell lines compared with non-metastatic melanoma and normal melanocytes." (PMID 21992144, 2011).
Nephropathy (1 paper, 2013). A nonspecific term referring to disease or damage of the kidneys. "Interestingly, differential expression of glomerular Nck1 between mouse strains carrying the nephropathy-prone 129/Sv allele and nephropathy-resistant C57BL/6 allele was also observed." (PMID 23441190, 2013). "Interestingly, Nck1 glomerular expression in mice with a nephropathy-prone mixed background of C57BL/6 and 129/Sv was almost 10-fold higher than that in nephropathy-resistant C57BL/6 mice." (PMID 23441190, 2013).
pancreatic cancer (1 paper, 2017). "Since invasiveness distinguishes gemcitabine-resistant from gemcitabine-sensitive cell lines, we hypothesize based on the network predictions that NCK1 affects the pancreatic cancer and gemcitabine resistance through invasiveness mechanisms." (PMID 29023490, 2017). "NCK1 has been demonstrated to affect pancreatic cancer migration but not growth through EGFR, a protein to which our networks also link NCK1." (PMID 29023490, 2017).